NPY (neuropeptide Y)
Diseases named in the same sentence as NPY in open-access papers (continued):
Sharing a sentence is not in itself a finding about the gene and the disease.
holoprosencephaly (1 paper, 2016). Holoprosencephaly (HPE) is a complex brain malformation resulting from incomplete cleavage of the prosencephalon, occurring between the 18th and 28th day of gestation, and affecting both the forebrain and face, which results in neurological manifestations and facial anomalies of variable severity. "Interestingly, in cases of human holoprosencephaly (HPE) with severe ventral forebrain hypoplasia, it was reported that only subpopulations of cortical interneurons (namely, those which express either NOS1, NPY, or SST) were absent, while calretinin-positive interneurons were still detected." (PMID 27069486, 2016).
Hydrocephalus (1 paper, 2023). Hydrocephalus is an active distension of the ventricular system of the brain resulting from inadequate passage of CSF from its point of production within the cerebral ventricles to its point of absorption into the systemic circulation. "In the present study, methodological and ethical concerns hindered us from evaluating the NPY levels in CSF, since this specific cerebrovascular cohort (without hydrocephalus) is not amenable to CSF diagnostics." (PMID 38425753, 2023).
Hyperkeratosis (1 paper, 2022). Hyperkeratosis is a histopathological term defining a thickened stratum corneum and may be present in many different skin conditions, with many possible overlaps. "Pathohistological and transcriptomic evaluation of these mice revealed that NPY-induced changes in skin architecture (e.g., fibrosis and hyperkeratosis), immune cell infiltration, and gene expression changes reminiscent of human inflammatory skin disease." (PMID 35418942, 2022).
hyperthyroidism (1 paper, 2012). Overactivity of the thyroid gland resulting in overproduction of thyroid hormone and increased metabolic rate. "In keeping with these data, we have recently reported that thyroid hormone-induced feeding, both short-term (central administration) and long-term (hyperthyroidism), is mediated by selective modulation of the mTOR pathway in the ARC, which elicits increased expression of AgRP and NPY." (PMID 23056530, 2012).
hypocortisolism (1 paper, 2010). "The pattern, in some CFS cases, of high NPY noted here, along with previously observed low DPPIV and hypocortisolism supports the hypothesis of HPA axis dysregulation in CFS." (PMID 21190576, 2010).
hypopharyngeal cancers (1 paper, 2018). Carcinoma, predominantly squamous cell, arising from the epithelial cells of the hypopharynx. "Patients with oral cavity cancers showed a significantly higher NPY methylation in comparison to patients with hypopharyngeal cancers (p = 0.003)." (PMID 29361757, 2018). "Notably, the less frequently methylated genes (less than 30%) were as follows: CDH13, p16, MGMT, GAL, NPY, GALR2, and VEGFR3 for hypopharyngeal cancers; CDH13, p16, RASSF1A, GAL, NPY, and NPY1R for laryngeal cancers; and CDH13 and GAL for oral cavity cancers." (PMID 29361757, 2018).
hypothyroidism (1 paper, 2021). Abnormally low levels of thyroid hormone. "Since the NPY mRNA level in patients did not change, we can assume that the mechanisms of influence of AIT and hypothyroidism, which lead to changes in the composition of neuropeptides, may not involve direct gene transcription, but TR mediates it." (PMID 34104248, 2021).
inflammatory skin disease (1 paper, 2022). Inflammatory skin disorders covers a broad category that includes many conditions ranging in severity, from mild itching to grave medical health complications These disorders are common in people of all ages and races. "Herein, we review what is currently known about the associations of NPY with these common inflammatory skin diseases." (PMID 35418942, 2022). "Given the association of NPY with inflammatory skin diseases, and the effect the NPY is known to have on T cell cytokine production and proliferation, further investigation on specific interactions between NPY and resident memory T cells is warranted." (PMID 35418942, 2022). "This review sets the stage for future investigations into the role of NPY in skin biology and pathology to stimulate research on therapeutic targeting NPY signaling in order to combat inflammatory skin diseases." (PMID 35418942, 2022).
intervertebral disc degeneration (1 paper, 2017). "Previous studies on intervertebral disc degeneration models have not addressed the expression of other sympathetic nervous system-related molecules, such as DBH, NPY, SOM, LENK, and GAL." (PMID 28762133, 2017).
intracranial hemorrhage (1 paper, 2023). Bleeding within the SKULL, including hemorrhages in the brain and the three membranes of MENINGES. "Compared to other types of intracranial hemorrhage, we observed an increased release of NPY into CSF to be specific for SAH." (PMID 38425753, 2023). "While a previous analysis of CSF NPY in SAH dismissed the influence of the treatment modality (EV vs. MS) on NPY secretion, our findings in UIA treatment (without any confounders like intracranial hemorrhage, CV, or additional surgical interventions) prove the contrary." (PMID 38425753, 2023).
ischemia reperfusion injury (1 paper, 2023). Adverse functional, metabolic, or structural changes in ischemic tissues resulting from the restoration of blood flow to the tissue (reperfusion), including swelling; hemorrhage; necrosis; and damage from free radicals. "To detect the role of NPY in different AKI models, we established ischemia reperfusion injury (IRI) AKI model in NPY WT and KO mice by clamping renal arteries for 35 minutes." (PMID 36632461, 2023).
keloid (1 paper, 2021). An irregularly shaped, elevated mark on the skin caused by deposits of excessive amounts of collagen during wound healing. "One of the over-expressed gene in the keloid samples, NPY, encodes a direct angiogenic stimulator that is known to stimulate cell proliferation." (PMID 34600545, 2021). "The mRNA levels of NPY, ADCY8, GNG13 and HTR1A were significantly augmented in keloid compared with normal skin samples ***p < 0.001." (PMID 34600545, 2021). "GNG13, ADCY8, NPY and HTR1A may act as core genes in keloid formation and these core genes establish relationship with SP1 and miRNA (hsa-mir-372, hsa-mir-20, hsa-mir-10b), which may influence multiple signaling pathways in the pathogenesis of keloid." (PMID 34600545, 2021).
leukemia (1 paper, 2023). A malignant (clonal) hematologic disorder, involving hematopoietic stem cells and characterized by the presence of primitive or atypical myeloid or lymphoid cells in the bone marrow and the blood. "Plasma NPY levels were higher in children with leukemia than those found in healthy individuals, and these plasma levels were also higher in children with an excellent clinical risk classification." (PMID 37373115, 2023). "Children with leukemia and a high plasma NPY level showed a better outcome." (PMID 37373115, 2023).
lubag syndrome (1 paper, 2022). "Another investigation has demonstrated a considerable decline in the NPY-positive cells, as well as the deprivation of axons within the two, namely caudate nucleus and putamen, of individuals experiencing lubag syndrome/X-linked dystonia of panay." (PMID 35562956, 2022). "Moreover, individuals with lubag syndrome/X-linked dystonia of panay have indicated the paucity of the labeling of NPY within the subventricular zone (SVZ), together with a consequential forfeiture of proliferating cell nuclear antigen (PCNA)-representing progenitor cells (PGCs)." (PMID 35562956, 2022).
lymph node metastasis (1 paper, 2023). "A high Y1R expression has been correlated with lymph node metastasis, advanced stages, and perineural invasion; an increased Y5R expression with survival and tumor growth; and a high serum NPY level with relapse, metastasis, and poor survival." (PMID 37373115, 2023).
meningioma (1 paper, 2023). A generally slow growing tumor attached to the dura mater. "Non-vascular microsurgery for convexity meningioma and lumbar degenerative spine disease did not significantly alter the amount of NPY in serum during the first 42 postoperative days." (PMID 38425753, 2023).
mental disorder (1 paper, 2025). A disease that has its basis in the disruption of mental process. "Targeting the neuropeptide Y1 (Y1R) and Y2 (Y2R) receptors has gained interest in treating weight and mental disorders." (PMID 40242586, 2025).
microcephaly (1 paper, 2020). A congenital or acquired developmental disorder in which the circumference of the head is smaller than normal for the person's age and sex. "Rbm8a cKO in neural stem cells results in early postnatal lethality, microcephaly, and leads to decreased number of PV+ and NPY+ cortical interneurons, abnormal distribution of PV+, SST+, and NPY+ interneurons in the cortex, and aberrant GABA transmission." (PMID 33154347, 2020).
morbid obesity (1 paper, 2020). An excess of body weight, normally defined as an individual with a body mass index greater than 35 or a body weight greater than one hundred percent of ideal body weight. "At high levels, leptin inhibits food intake through the melanocortin receptor system, and at low levels, it promotes food intake through neuropeptide Y. Mutations in the LEPR gene result in leptin insensitivity, hyperphagia, morbid obesity, and metabolic and endocrine abnormalities." (PMID 31480192, 2020).
multiple sclerosis (1 paper, 2017). A progressive autoimmune disorder affecting the central nervous system resulting in demyelination. "The number of NPY-Y1R+ axons in multiple sclerosis PPWM was significantly higher in the early as compared to the chronic disease stage (early; 113.6 ± 7, chronic; 4.6 ± 0.8 profiles/mm2; ***p < 0.001)." (PMID 28302146, 2017). "Using NPY-Y1R immunohistochemistry, Wallerian degeneration was quantified in areas of PPWM brain tissue from 31 multiple sclerosis patients." (PMID 28302146, 2017). "We observed widespread occurrence of NPY-Y1R+ degenerating axonal fibers in non-demyelinated PPWM areas in multiple sclerosis patients." (PMID 28302146, 2017).
narcolepsy (1 paper, 2009). A sleep disorder characterized by a tendency for excessive sleepiness during the day which occurs even after adequate sleep in the nighttime. "The other downregulated genes that were found, or previously known to express elsewhere (eg NPY, GPR4), may reflect physiologically important network remodeling in narcolepsy." (PMID 19158946, 2009).
nasal obstruction (1 paper, 2011). "Previous studies showed that NPY induces vasoconstriction and that local pre-treatment with exogenous NPY in a nasal allergen challenge leads to a reduction of both nasal obstruction and mucus secretion, suggesting a protective effect of NPY on both vasodilation and secretory responses." (PMID 21245958, 2011).
osteonecrosis of (1 paper, 2022). "Our study aimed at investigating the impact of NPY-Y1R signaling in the pathogenesis of glucocorticoid-related osteonecrosis of the femoral head (ONFH)." (PMID 36428510, 2022).
ovarian tumor (1 paper, 2023). "NPY also exerted a protective action against cisplatin and improved bone marrow dysfunction in an ovarian tumor murine model." (PMID 37373115, 2023). "NPY exerted a protective action against cisplatin and improved bone marrow dysfunction in an ovarian tumor murine model." (PMID 37373115, 2023).
pneumonia (1 paper, 2024). An acute, acute and chronic, or chronic inflammation focally or diffusely affecting the lung parenchyma, caused by an infection in one or both of the lungs (by bacteria, viruses, fungi, or mycoplasma.). "The present study revealed for the first time that plasma levels of neurogenic inflammation-related CGRP and VIP neuropeptides increased and NPY levels decreased in pediatric patients with pneumonia." (PMID 38183438, 2024). "When analyzed according to pneumonia subgroups, it is understood that this decrease in NPY levels is due to patients with viral pneumonia." (PMID 38183438, 2024). "In contrast, plasma level of NPY was significantly lower in patients with pneumonia than in the control group (p = 0.002)." (PMID 38183438, 2024). "Unlike the other neuropeptides, we found that NPY levels were lower in patients with general pneumonia compared to the healthy controls." (PMID 38183438, 2024).
polyp (1 paper, 2021). A usually exophytic mass attached to the underlying tissue by a broad base or a thin stalk. "Currently a tumor-promoting role for NPY is suggested, based on observations that NPY-deficient mice displayed reduced inflammation, polyp size, and polyp number in an inflammation model (DSS), and that NPY stimulates proliferation and reduces apoptosis of tumor cells in vitro." (PMID 33466373, 2021).
progeria (1 paper, 2025). "In this regard, some compounds with the ability to induce progeria degradation through autophagy activation have been previously identified, including rapamycin (inhibitor of mTOR pathway), MG132 (proteasome inhibitor), sulforaphane (antioxidant compound) and neuropeptide Y." (PMID 39871520, 2025).
prostate (1 paper, 2023). "Because of this, the NPY neural microenvironment plays a vital role in prostate oncogenesis and therapy resistance, and the NPY system is a potential antitumor target in this disease." (PMID 37373115, 2023).
pubertal delay (1 paper, 2015). "Furthermore, in one study, NPY levels were higher in girls with CDGP than a group of girls with normal pubertal timing, suggesting that it, and possibly other related receptors, may be important in pubertal delay." (PMID 26030606, 2015).
pulmonary fibrosis (1 paper, 2024). Chronic progressive interstitial lung disorder characterized by the replacement of the lung tissue by connective tissue, leading to progressive dyspnea, respiratory failure, or right heart failure. "Unlike the other neuropeptides (CGRP, SP and VIP), NPY is a vasoconstrictor and also promotes angiogenesis and blocked generation of pulmonary fibrosis through inhibition of IL-1β." (PMID 38183438, 2024).
pulmonary hypertension (1 paper, 2018). Increased pressure within the pulmonary circulation due to lung or heart disorder. "Additionally, although no studies have examined the effects of modulating NPY in COPD, the NPY antagonist BIBO 3304 has purported beneficial effects in pulmonary hypertension." (PMID 30081920, 2018). "Therefore, it is possible that NPY modulation might be of benefit in some people with COPD, such as those that have pulmonary hypertension." (PMID 30081920, 2018).
retinal (1 paper, 2024). "As a novel finding, this study has identified changes in the expression levels of endogenous NPY and a subset of its receptors under retinal degenerative conditions induced by elevated IOP." (PMID 39114576, 2024).
Sensory neuropathy (1 paper, 2018). Peripheral neuropathy affecting the sensory nerves. "In this study, we identified novel peptides, generated from full-length NPY that rescued cisplatin-induced sensory neuropathy and HSC suppression by regulating cell survival in the BM microenvironment." (PMID 30460109, 2018).
small intestinal disease (1 paper, 2021). "In our experiment, NSAID-induced small intestinal disease model rats intervened by berberine showed significantly change in HTR4, F2RL3, NPY, CRHR2, IL1b, VIP, AQP8, NOS1." (PMID 34284820, 2021).
spinal cord inflammation (1 paper, 2014). "G-CSF prevented the upregulation of NPY, a well-known neuropeptide involved in energetic metabolism and food intake but also expressed by neurons in response to stress such as spinal cord inflammation." (PMID 25653590, 2014).
squamous cell carcinoma (1 paper, 2016). A carcinoma arising from squamous epithelial cells. "In 2004, Lee proposed that neuropeptide Y is increased in squamous cell carcinoma patients which in turn increases endogenous AVP production leading to SIADH." (PMID 27635269, 2016).
steatosis (1 paper, 2023). Increased lipid within the cytoplasm of cells. "Histopathological analysis showed steatosis was accompanied, in males only, by up-regulation of NPY expression at both dose levels." (PMID 37755786, 2023). "Indeed, steatosis was more marked in female rats, but NPY expression was unaltered." (PMID 37755786, 2023).
T-cell leukemia (1 paper, 2023). A malignant disease of the T-lymphocytes in the bone marrow, thymus, and/or blood. "A high NPY mRNA level was observed in the bone marrow of children with B-cell precursor leukemia, but no NPY mRNA was reported in children with T-cell leukemia." (PMID 37373115, 2023).
vascular ED (1 paper, 2021). "Under various stress conditions, increases in NPY level in the central and/or peripheral nervous system is directly and indirectly involved in the process of vascular ED, thus participating in the pathophysiological process of vascular diseases." (PMID 34512386, 2021).
Vasovagal syncope (1 paper, 2021). A vasovagal episode or vasovagal syncope is the most common form of reflex syncope. "A study by Peking University showed that plasma NPY is significantly reduced in Vasovagal Syncope, which may participate in the pathogenesis of Vasovagal Syncope by increasing total peripheral vascular resistance and reducing cardiac output." (PMID 34422139, 2021).
Vestibular schwannoma (1 paper, 2021). A vestibular schwannoma (also known as acoustic neuroma, acoustic neurinoma, or acoustic neurilemoma) is a benign, usually slow-growing tumor that develops from the VIIIth cranial nerve supplying the inner ear. "Low expression of COL4A1 and COL5A1 was associated with recurrence of vestibular schwannoma; while high expression of NPY was associated with recurrence of vestibular schwannoma." (PMID 34691289, 2021). "We speculate that NPY may have a potential relevance to the recurrence of vestibular schwannoma by regulating vascular-related function." (PMID 34691289, 2021). "Finally, the relevance of NPY to vestibular schwannoma was also revealed for the first time." (PMID 34691289, 2021).
viral pneumonia (1 paper, 2024). Inflammation of the lung parenchyma that is caused by a viral infection. "More studies need to clarify the reasons for the decrease in NPY levels in pediatric patients with viral pneumonia." (PMID 38183438, 2024). "Plasma levels of NPY were significantly higher in patients with bacterial/mixed compared to both the control and viral pneumonia groups, respectively (p = 0.001 and p = 0.001)." (PMID 38183438, 2024). "However, plasma levels of NPY were significantly lower in patients with viral pneumonia compared to the control group (p < 0.001)." (PMID 38183438, 2024). "In the current study, the decrease in neuropeptide Y levels in viral pneumonia cases may be related to the decrease in this early stage." (PMID 38183438, 2024). "It is interesting that NPY levels were lower in patients with viral pneumonia in the current study." (PMID 38183438, 2024).
vision disorder (1 paper, 2024). Any impairment to the vision. "The pro-angiogenic function of NPY, although exerting a positive impact on vascular recanalization and wound healing in ischemic tissues, may concurrently induce negative influences such as tumorigenesis and vision disorders." (PMID 39539691, 2024).
xerosis (1 paper, 2024). "A study demonstrated that the loss of cutaneous touch receptors, specifically Merkel cells, leads to increased alloknesis during aging and in xerosis, indicating that inputs from SAI Aβ-LTMRs may attenuate the gating activity of NPY+ interneurons." (PMID 39602426, 2024).